STAT3 (signal transducer and activator of transcription 3)
Diseases named in the same sentence as STAT3 in open-access papers (continued):
Sharing a sentence is not in itself a finding about the gene and the disease.
bladder cancer (continued). "STAT3 activation was crucial for exhibition of malignant characteristics in T24 bladder cancer cells, indicating that STAT3 signaling pathway represents as a potential therapeutic target for bladder cancer." (PMID 22811589, 2012). "Inhibition of Stat3 pathway suppressed cell growth of bladder cancer cells in vitro." (PMID 18939995, 2008). "The Stat3 signaling pathway appears as a potential target for bladder cancer therapy." (PMID 18939995, 2008). "In addition, elevated p-Stat3 expression was also found in bladder cancer cell lines, UMUC-3, 253J and WH." (PMID 18939995, 2008). "It remains unclear whether oncogenic Stat3 signaling pathway is involved in the oncogenesis of bladder cancer." (PMID 18939995, 2008). "The role of activated Stat3 in bladder cancer remained speculative until the recent report showed that Stat3 activation correlated with malignant characteristics of T24 bladder cancer cells." (PMID 18939995, 2008). "Therefore, interference of Stat3 signaling pathway emerges as a potential therapeutic approach for bladder cancer." (PMID 18939995, 2008). "Elevated p-Stat3 expression is also found in bladder cancer cells, UMUC-3, WH and T24." (PMID 18939995, 2008). "Nineteen out of 100 bladder cancer tissues were positive for p-Stat3 immunostaining (scale 2–3)." (PMID 18939995, 2008). "All bladder cancer cell lines examined have very similar total Stat3 expression levels." (PMID 18939995, 2008). "It appears that targeting dnStat3 signaling pathway could be an effective therapeutic approach for bladder cancer expressing constitutive activation of Stat3." (PMID 18939995, 2008). "We found that elevated p-Stat3 expression is found in both bladder cancer tissues and cell lines." (PMID 18939995, 2008). "Our data suggest that bladder cancer cells might utilize Stat3 signaling pathway for cell growth and survival." (PMID 18939995, 2008). "Taken together, Stat3 activation may play a pivotal role in bladder cancer cell growth and survival and serve as a novel therapeutic target for this type of cancer." (PMID 18939995, 2008). "Our data, consistent with previous studies, has delineated part of the relationship between elevated p-Stat3 expression and bladder cancer, although mechanisms for cell growth inhibition and cell death by dnStat3 in bladder cancer cell UMUC-3 and WH remain largely unclear." (PMID 18939995, 2008). "Our data show that Stat3 phosphorylation is elevated and may play a pivotal role in cell growth and survival of bladder cancer." (PMID 18939995, 2008). "To investigate whether STAT3 binds to the promoter region of ERCC4 and how CXCL14 enhances its expression in bladder cancer cells, we overexpressed STAT3 in 293 T cells as an external validation and modulated STAT3 phosphorylation in T24 cells with rhCXCL14 or rhCXCL14 combined with STAT3i." (PMID 40898244, 2025). "Additionally, the combination of cisplatin-based chemotherapy with CCR7 or STAT3-targeted therapies may offer a more effective treatment strategy for patients with bladder cancer." (PMID 40898244, 2025). "Moreover, we observed significant enrichment of the JAK/STAT3 pathway in basal bladder cancer." (PMID 39840049, 2024). "One mechanism that might explain how this effect is mediated was explored in a bladder cancer model in which metformin was able to inhibit stem cell multiplication by reducing COX-2-mediated PGE2 and following STAT3 activation both in mouse bladder cancer and bladder cancer cell lines." (PMID 38791445, 2024). "Therefore, we speculated that STAT3 inhibitors also could also enhance RC48 efficacy against basal bladder cancer." (PMID 39840049, 2024). "In vitro experiment was used to validate that osthole had cytotoxic effect on bladder cancer cells and inhibited the migration, EMT process by inhibiting the PI3K-AKT-mTOR, JAK/STAT3 pathway.Above all, osthole may provide a new treatment idea for bladder cancer." (PMID 37069622, 2023).
bladder cancer (continued). "Taken together, our findings reveal that Foxp1 promoted the occurrence and development of bladder cancer through the Warburg effect by the activation of STAT3 activity and repressing β-AR transcription, and which might serve as an important clue for its targeting and treatment of bladder cancer." (PMID 37663229, 2023). "Furthermore, RORC, via blocking STAT3, might have sensitized bladder cancer cells’ response to cisplatin." (PMID 36230984, 2022). "For example, lncRNA UCA1 could activate the mTOR pathway, mediate the regulation of urothelial cancer associated 1 (UCA1) to HK2 through activation of signal transducer and activator of transcription 3 (STAT3), then promote glycolysis, exert promotion effects on tumorigenesis in bladder cancer." (PMID 36072431, 2022). "In addition, it was revealed that an elevated amount of RORC, with expression that is considered to be downregulated in bladder cancer, has probably led to the inhibition of cell proliferation and glucose metabolism, by suppressing the binding of STAT3 to the promoter of STAT3-mediated genes." (PMID 36230984, 2022). "GSDMB could bind to intracellular STAT3 and activate the STAT3 signaling pathway in bladder cancer." (PMID 36338999, 2022). "We also found that BUB1 was positively related to STAT3 based on TCGA data in the online GEPIA database (R = 0.21; P < 0.05), which further supports the hypothesis that BUB1 might regulate the progression and prognosis of bladder cancer by mediating the STAT3 signaling pathway." (PMID 34852826, 2021). "Furthermore, we showed that USP24 could stabilize GSDMB, and the USP24/GSDMB/STAT3 signaling axis provided some potential therapeutic targets for bladder cancer." (PMID 34326684, 2021). "Therefore, further exploring the regulatory mechanism of STAT3 in cells could provide therapeutic strategies for bladder cancer." (PMID 34326684, 2021). "Therefore, the USP24/GSDMB/STAT3 axis may be a new targetable signaling pathway for bladder cancer treatment." (PMID 34326684, 2021). "Moreover, the PD-L1/ITGA6 axis promotes STAT3 nucleus translocation in bladder cancer." (PMID 34326684, 2021). "Then, we showed that GSDMB could bind to STAT3 and activate STAT3 signaling in bladder cancer." (PMID 34326684, 2021). "Thus, STAT3 is considered to be an ideal target for bladder cancer therapy." (PMID 34326684, 2021). "Considering these findings, we explored targeting of the JAK1/2 and STAT3/5 proteins using specific small molecule inhibitors and combined these inhibitors with standard chemotherapy, inhibitors of cell cycle progression and oncolytic adenovirus in preclinical models of bladder cancer." (PMID 32046095, 2020). "Thus, we hypothesize that HMGN5 may interact with Hsp27 to affect IL-6-induced EMT and invasion in bladder cancer by modulating STAT3 phosphorylation and STAT3 targeting of the Twist promoter." (PMID 32315283, 2020). "In conclusion, Our results showed a good correlation of the expression patterns of both the cell cycle (CDK4) and inflammatory (STAT3) markers studied and might be helpful for suggesting more selective agents in the therapeutic scenario of bladder cancer in the near future." (PMID 32102537, 2020). "In our study, we show that STAT3 inhibition has an additive effect when combined with the most frequently used chemotherapeutic drugs approved for bladder cancer suggesting that this combination might be applicable in patients with STAT3 mediated chemo resistance." (PMID 32046095, 2020). "Moreover, HMGN5 could modulate IL-6-Hsp27-induced EMT and invasion in bladder cancer cells by regulating STAT3 phosphorylation and STAT3-mediated Twist transcription." (PMID 32315283, 2020). "In fact, we could show, both in tissue samples where we could find evidence of physical proximity, but also in the T24 bladder cancer cell line, where Stat3 activation potentiated interaction of activated Stat3 with Blcap, that Blcap physically interacts with Stat3." (PMID 29190807, 2017).
bladder cancer (continued). "Of note, interruption of STAT3 signaling pathway by either knockdown STAT3 or overexpression of dominant negative form of STAT3 induces cell growth arrest and apoptosis, indicating that targeting STAT3 signaling is a promising therapeutic approach for bladder cancer patients." (PMID 25849286, 2015). "Majorities of bladder cancer tissues examined are negative for p-Stat3 and may result from other causes for this kind of cancer." (PMID 18939995, 2008). "This implicates that activation of Stat3 may play a role in the development of bladder cancer." (PMID 18939995, 2008). "Bladder cancer (BCa) exhibits SULF2-mediated IL-8 secretion through β-catenin, inducing M2 macrophage polarization via the JAK2/STAT3 signaling pathway." (PMID 40959082, 2025). "IHC analysis demonstrated that STAT3 inhibition decreases TLR activation and suppresses proliferation in bladder cancer cell lines." (PMID 40708946, 2025). "Specifically, CXCL14 activates the CCR7/JAK2/STAT3 axis, leading to the upregulation of ERCC4 transcription, which promotes DNA damage repair in bladder cancer cells, thereby facilitating the development of chemoresistance." (PMID 40898244, 2025). "In metastatic bladder cancer, exemplified by the T24T cell line, miR-145 upregulates FOXO1 expression by inhibiting the phosphorylation of STAT3 at the Tyr705 site, thereby disrupting its repression of FOXO1 transcriptional activity." (PMID 40689207, 2025). "Collectively, our results suggest that CAF-derived CXCL14 targets CCR7 in bladder cancer cells, enhancing ERCC4 transcription through JAK2/STAT3 activation and subsequently binding to the ERCC4 promoter region." (PMID 40898244, 2025). "For example, with network pharmacology, it has been found that osthole can inhibit bladder cancer cell migration, invasion, and epithelial-mesenchymal transition by regulating PI3K/AKT and JAK/STAT3 signaling pathways." (PMID 41287122, 2025). "Inhibition of STAT3 by Napabucasin, a Phase II/III FDA-approved drug, significantly abrogated the capacity of DDR1-expressing cancer cells to form lung metastases from bladder cancer." (PMID 38907027, 2024). "For example, activation of STAT3 mediated CXCL12 upregulation in the dorsal root ganglion and was essential for CXCL12-induced cell invasion in bladder cancer." (PMID 38338982, 2024). "IL-6 promotes bladder cancer progression through AKT and STAT3 activations which ultimately lead to epithelial-mesenchymal transition and angiogenesis." (PMID 38172584, 2024). "In bladder cancer tissues, a positive correlation exists between elevated CXCR4 expression and positive p-STAT3 expression." (PMID 38920657, 2024). "MiR-21 from bladder cancer directly downregulates PTEN and increases PI3K/Akt signaling activity while activating STAT3." (PMID 38523627, 2024). "It is interesting to highlight the previous work showing that STAT3 transcriptionally upregulates LDHA in thyroid and bladder cancer cells." (PMID 38443336, 2024). "The strong responsiveness of MMP1 to EGF relies on STAT3 phosphorylation and its interaction with c-JUN, and with this crucial activation of STAT3, T24 cells exhibit malignant characteristics in bladder cancer." (PMID 38320998, 2024). "STAT3’s role in inducing epithelial-mesenchymal transition (EMT) is a key mechanism in cancer invasion and metastasis, making it significant in bladder cancer progression." (PMID 39450166, 2024). "In bladder cancer, PRDX6 promoted the proliferation and cell cycle of bladder cancer cells through JAK2/STAT3 signalling pathway." (PMID 38506082, 2024). "We found that osthole had cytotoxic effect on bladder cancer cells and inhibited invasion, migration, and epithelial-mesenchymal transition by inhibiting PI3K-AKT and JAK/STAT3 pathways in in vitro experiment." (PMID 37069622, 2023). "Signal transducer and activator of transcription 3 (STAT3) signaling pathway was reported to induce chemoresistance and EMT via MMP-9 induction in bladder cancer." (PMID 35586209, 2022).
bladder cancer (continued). "Taken together, SENP3 promotes bladder cancer proliferation and EMT transformation by regulating STAT3." (PMID 36227136, 2022). "In our study, we examined the regulation of STAT3 post-translational modifications (PTMs) and found that SENP3 is high in bladder cancer." (PMID 36227136, 2022). "Considering the oncogenic role of RACGAP1 in the malignant behaviors of bladder cancer cells, we inferred that RACGAP1 exerts cancer-promoting functions via the upregulation of p-STAT3, active RhoA, and p-ERK1/2." (PMID 35013128, 2022). "STAT3 inhibition led to PCSC sensitization to cisplatin in PCa and bladder cancer and docetaxel in PCa." (PMID 36230984, 2022). "SENP3/STAT3/PYCR1 pathway promoted the viability, proliferation, invasion and EMT of bladder cancer cells." (PMID 36227136, 2022). "Our findings revealed that HME inhibits both constitutive and IL-6-induced STAT3 activation in human bladder cancer cells, supporting HME as an inhibitor of STAT3 activation." (PMID 36613579, 2022). "Meanwhile, SENP3 promoted the phosphorylation of STAT3 to address the relationship between SENP3 and STAT3 in bladder cancer, SENP3 and STAT3 proteins were detected in 8 cases of bladder cancer and para-cancerous tissues." (PMID 36227136, 2022). "STAT3 has been reported to be SUMOylation in tumors, and SENP3 expression in bladder cancer tissue was higher than that in adjacent or normal tissue." (PMID 36227136, 2022). "In all, this study tested STAT3 and SENP3 expression in bladder cancer tissues and examined its connection and molecular mechanism in bladder cancer." (PMID 36227136, 2022). "Abnormal activation of signal transducer and activator of transcription 3 (STAT3) has been found in various types of human cancers, including bladder cancer (BC)." (PMID 36227136, 2022). "Aspirin inhibited cell adhesion to FN and the cell invasiveness of PC-3 (a bladder cancer cell line) and suppressed scar markers, including FN, and scar formation through JNK/STAT-3 in a tendon injury rat model." (PMID 36558974, 2022). "STAT3 in the nucleus upregulated the expression of oncogene pyrroline-5-carboxylate reductase 1 (PYCR1), which promoted bladder cancer proliferation and EMT." (PMID 36227136, 2022). "In conclusion, we present the first evidence of HME’s anti-bladder cancer effect, likely proceeding by evoking apoptosis through suppression of the antiapoptotic SRC/STAT3/survivin signaling axis." (PMID 36613579, 2022). "lnc-STYK1-2 inhibited bladder cancer cell proliferation, migration, and tumorigenesis by targeting miR-146b-5p to regulate ITGA2 expression and AKT/STAT3/NF-kB signaling." (PMID 34332611, 2021). "Such novel findings indicated that bladder cancer cells enhanced CXCL9 in TADCs, which significantly up-regulated PD-L1 expression in cancer cells by activating the CXCR3-related STAT3/Akt signaling." (PMID 33407095, 2021). "To further understand how the increased CXCL9 expression by TADCs regulated PD-L1 expression in bladder cancer T24 cells, we tested the effect of CXCL9 treatment on the expression of STAT3 and Akt activation in T24 cells by Western blot." (PMID 33407095, 2021). "The data were also comparable to Rieger-Christ’s finding that EGCG decreased the migratory potential of bladder-carcinoma cells with concomitant activation of MAPK and STAT3 and downregulation of N-cadherin." (PMID 33747527, 2021). "Together, these results revealed that ITGA2 and AKT/NFκB/STAT3 signaling pathways were regulated by lnc-STYK1-2 and miR-146b-5p in bladder cancer cells." (PMID 34332611, 2021). "Overexpressed GSDMB promoted cancer cell growth via interacting with STAT3 to elevate the phosphorylation level of STAT3, which increased the expression of HK2, LDNA, ENO2, and IGFBP3 to enhance the glycolysis of bladder cancer cells." (PMID 34326684, 2021).
bladder cancer (continued). "Mechanism studies reported that altholactone inhibited the growth of human bladder cancer T24 cells (IC50 = 43.5 μM) by inducing apoptosis and induced DU145 cell death (IC50 = 38.5 μM), through inhibition of NF-κB and STAT3 activity." (PMID 32455540, 2020). "Although AKR1C1 is reported to be involved in tumour metastasis through interaction with STAT3 in NSCLC27 and to promote invasion of bladder cancer cells, evidence supporting the facilitation of metastasis is still lacking." (PMID 32307891, 2020). "Upon IL-6 stimulation, HMGN5/Hsp27 modulates bladder cancer EMT and bladder cancer cell invasion via the STAT3/Twist signaling pathway." (PMID 32315283, 2020). "Our current study further demonstrated that miR-153's anti-tumor activity in bladder cancer cells was mediated by targeting IDO1, which in turn inactivated the IL6/STAT3/VEGF signaling pathway." (PMID 31355138, 2019). "We found that, IL-6 expression was significantly suppressed in the experimental groups compared to the control groups, while phosphorylated STAT3 and VEGF were also significantly decreased in miR-153-overexpressing or IDO1 knocked down bladder cancer cells." (PMID 31355138, 2019). "A previous study reported that overexpression of BMX in bladder cancer cells elevated the activity of AKT and STAT3, whereas knockdown of BMX had the opposite effect." (PMID 28514765, 2017). "In bladder cancer, S1PR1 signaling in T cells can drive Treg accumulation in tumors through JAK/STAT3 activation, resulting in promoting BCa growth." (PMID 29190997, 2017). "The activation of Signal Transducer and Activator of Transcription 3 (STAT3) is frequently detected in various cancer types, including bladder cancer." (PMID 25849286, 2015). "Increased STAT3 phosphorylation has also been observed in EGFR mAb treatment-resistant cell models of head and neck squamous carcinoma (HNSCC) and bladder cancer." (PMID 24280348, 2013). "Activation of STAT3 and ERK1/2 by nicotine modulates cell proliferation in human bladder cancer cells." (PMID 23620780, 2013). "In our own laboratory, we have also demonstrated that nicotine-induced cyclin D1 overexpression is regulated via Stat3, ERK1/2, and NF-κB-dependent pathways in bladder cancer cells." (PMID 21559255, 2011). "Cell growth inhibition and apoptosis can be induced in bladder cancer cell lines using either a dnStat3 or a small molecule inhibitor, STA-21 to interfere with the Stat3 signaling pathway." (PMID 18939995, 2008). "Interruption of Stat3 pathway by dnStat3 and STA-21 leads to activation of caspase 3 signaling in bladder cancer cells." (PMID 18939995, 2008). "A recent study shows that overactive Stat3 serves as the signal mediator between EGF and MMP-1 for bladder cancer cell migration, invasion and tumor formation." (PMID 18939995, 2008). "Furthermore, as a well-recognized transcriptional target of STAT3, BCL-xL expression has been identified as a poor prognostic marker for bladder cancer." (PMID 39997178, 2025). "Given that signaling pathways play important roles in the transcriptional modulation of key cellular regulators, we identified STAT3 as a potential transcriptional regulator of ERCC4, whichwas positively correlated with ERCC4 expression in bladder cancer patients in the TCGA cohort." (PMID 40898244, 2025). "In addition, EZH2 is highly expressed in bladder cancer, while JAK2/STAT3 signalling pathway is abnormally activated." (PMID 38506082, 2024). "In bladder cancer, cells with doxorubicin (DOX) and cisplatin (CIS) chemoresistance, accompanied by STAT3 activation, showed that the resistance could be reversed by a STAT3 inhibitor." (PMID 39840049, 2024).